LIFR (LIF receptor subunit alpha)
Diseases named in the same sentence as LIFR in open-access papers (continued):
Sharing a sentence is not in itself a finding about the gene and the disease.
breast tumor (10 papers, 2007 to 2024). "Specifically, the PTHrP C-terminal domain appears to function as an oncogenic molecular switch able to induce proliferation and promote primary breast tumor formation through a partially LIFR-dependent mechanism that suppresses p27 expression." (PMID 38409028, 2024). "The downstream signaling mechanisms by which LIFR regulates breast tumor growth remain incompletely understood." (PMID 38409028, 2024). "Recently, small molecule inhibitors and neutralizing antibodies targeting LIFR have been investigated as a strategy to inhibit breast tumor growth and metastasis in preclinical studies." (PMID 38409028, 2024). "Our results using breast tumor tissues are also in agreement with published studies that TNBC tumors have higher level of LIFR." (PMID 34716410, 2021). "Chen and co-workers reported that LIFR inhibited metastasis of breast tumor through the inactivation of YAP protein in Hippo-YAP pathway." (PMID 32651426, 2020). "In this study, we investigated the consensus of LIF and LIFR immunization on the growth of breast tumors after transplantation of the BTICs into breast fat-pad." (PMID 32651426, 2020). "LIFR is a known dormancy regulator in breast tumor cells in the primary and bone metastatic sites." (PMID 38409028, 2024). "Thus, repression of LIFR either directly or perhaps through PTHrP overexpression can push bone-disseminated breast tumor cells out of dormancy." (PMID 33828987, 2021). "Expression of LIF and LIFR by the breast tumors were studied." (PMID 32651426, 2020). "Hence, in this study, we investigated the consensus of LIF and LIFR immunization on the development of breast tumors in mice." (PMID 32651426, 2020). "Moreover, leukemia inhibitory factor receptor (LIFR), promotes dormancy of disseminated breast tumor cells in the bone." (PMID 31817646, 2019). "Thus, we hypothesized that PTHrP may regulate tumor cell proliferation through p27 signaling downstream of LIFR, resulting in altered breast tumor cell proliferation." (PMID 38409028, 2024). "Another study demonstrated that leukemia inhibitory factor receptor (LIFR), whose ligand is a member of the interleukin-6 (IL-6) family of cytokines, confers a dormant phenotype of disseminated breast tumor cells." (PMID 34064392, 2021). "While the contribution of the individual gp130 cytokines to tumor dormancy has not been fully resolved, LIFR has been shown to promote tumor dormancy and function as a breast tumor suppressor." (PMID 32023849, 2020). "Furthermore, ILEI is an oncogenic cytokine that can bind to LIFR and trigger EMT and CSC traits of breast tumors via STAT3 activation." (PMID 32651426, 2020).
colorectal cancer (9 papers, 2015 to 2025). A primary or metastatic malignant neoplasm that affects the colon or rectum. "It was reported that LIFR promoted tumor angiogenesis by upregulating IL-8 levels in colorectal cancer." (PMID 36062165, 2022). "Our CpG set also included three known biomarker genes for colorectal cancer (LIFR, OSMR, QKI)." (PMID 38336771, 2024). "Additionally, the mutational frequency was >10% in 8 other TSGs in colorectal cancer: FAT4 (19%), TOPORS (15%), PPP2CB (13%), RASL11A (13%), PCDH9 (12%), PRDM2 (12%), LIFR (11%) and TGFBR2 (11%)." (PMID 26590405, 2016). "Colorectal cancer (CRC) is the second deadliest malignant disease in the world and the leukemia inhibitory factor receptor/signal transducers and activators of transcriptions (LIFR/STATs) signaling axis plays an important role in the molecular biology of CRC." (PMID 33505963, 2020).
Infertility (9 papers, 2017 to 2025). "MR results revealed genetic correlations between abnormal ADA, artemin, OSM, caspase 8, CXCL5, interleukin‐18, and LIFR levels and infertility." (PMID 40525280, 2025). "Although the reason behind this unexpected result remains to be investigated, it is possible that a balanced LIF/LIFR signal is critical for successful pregnancies; both too little and too much LIF production can cause infertility." (PMID 36329823, 2022). "Notably, the reduced expression of LIFR in the endometrial epithelium has been reported in women with unexplained infertility, suggesting that our findings may contribute to the identification of markers for endometrial receptivity in humans." (PMID 40427591, 2025). "It has been revealed that compared to fertile women, women with unexplained infertility have high endometrial levels of the inhibitor of LIF, SOCS1, accompanied by low levels of LIF receptor (LIFR) and gp130." (PMID 34496883, 2021).
lung carcinoma (9 papers, 2017 to 2025). "Given that the lack of correlation between FAM3C expression and its known receptor LIFR in lung cancer, it signifies the need to elucidate the underlying mechanisms of its signal transduction." (PMID 36632230, 2023). "In brief, this study showed that disseminated cancer cells underwent MET by the LIFR/p-ERK/pS727-STAT3 signalling pathway in early stages of lung cancer metastasis, acquiring enhanced sphere-forming ability and proliferative potential." (PMID 34361105, 2021). "Interestingly, LIF promoted mesenchymal epithelial transition in lung cancer cells through the LIF/LIFR/p-ERK/pS727-STAT3 signalling pathway leading to increased metastasis." (PMID 34361105, 2021). "Specifically, in the context of lung cancer, bone marrow‐derived mesenchymal stem cells secrete LIF, which subsequently engages the LIFR/p‐ERK/pS727‐STAT3 signaling pathway, thereby modulating the balance between EMT and its reverse process, MET." (PMID 40416597, 2025). "COBRA using TaqI (5′-TCGA-3′) showed that the LIFR promoter was methylated specifically in the colon cancer cell lines but not in the liver and lung cancer cell lines." (PMID 28751909, 2017).
Stüve-Wiedemann syndrome (9 papers, 2007 to 2025). "For example, biallelic LoF mutations in the LIFR gene cause Stüve-Wiedemann syndrome-1 (STWS1; OMIM:601559), a fatal neonatal disorder characterized by skeletal dysplasia, feeding difficulties, respiratory distress, and hyperthermia." (PMID 39847438, 2025). "Patients with homozygous amorphic mutations in IL6ST or LIF receptor (LIFR) develop Stüve-Wiedemann syndrome." (PMID 40526438, 2025). "This skeletal effect is partly transferable to humans, where mutations in the LIFR gene cause Stüve-Wiedemann syndrome (OMIM #610559), characterized by bowing and thickening in the lower limbs and abnormal trabecular bone structure." (PMID 35775083, 2022). "Of note, congenital mutations of the LIFR gene are seen to cause Stüve-Wiedemann syndrome, which presents phenotypically with skeletal abnormalities such as bowed long bones and joint restrictions, dysautonomia, and respiratory and feeding difficulties." (PMID 35204717, 2022). "Abbreviations: SWS = Stuve-Wiedemann syndrome, IVCM = in vivo confocal microscopy, CNTF = ciliary neurotrophic factor, BCVA = best corrected visual acuity, LIFR = Leukemia Inhibitory Factor Receptor, IGF1 = Insulin-like growth factor-1." (PMID 38239413, 2023).
COVID-19 (7 papers, 2021 to 2024). A disease caused by infection with severe acute respiratory syndrome coronavirus 2. "In particular, we found that the level of LIF and its soluble receptor LIFR were negatively co-regulated; the genetic components defining higher levels of LIF and lower levels of LIFR served as causal contributors to the severity of COVID-19 phenotypes." (PMID 38455043, 2024). "Meanwhile, five proteins exert protective effects against hospitalization and progression to critical COVID-19 (OR: 0.85~0.95), including CXCL11, CDCP1, CCL4/MIP, IFNG, and LIFR." (PMID 38455043, 2024). "The shared LIFR leukemia inhibitory factor receptor (M151443) with immunoglobulin/cytokine domains and the NLRP3 (M606416) pyrin-like genes could be involved in the inflammatory response to COVID-19 as well as the enhanced inflammation from adrenergic stimulation in EDS and other conditions." (PMID 37504295, 2023).
Obesity (7 papers, 2021 to 2025). Accumulation of substantial excess body fat. "The use of EC359 to inhibit LIFR offers a novel therapeutic approach for managing obesity-associated TNBC, addressing a critical need for effective treatments in the TNBC population." (PMID 39518071, 2024). "This study’s findings demonstrate that the obesity-associated microenvironment promotes TNBC progression through the upregulation of LIFR signaling." (PMID 39518071, 2024). "Future studies that examine the efficacy of LIFR inhibitor on obesity-associated EC are clearly needed and are beyond the scope of the present study." (PMID 34400617, 2021). "Collectively, our results suggest targeting LIFR signaling as a potential treatment for obesity-related TNBC." (PMID 39518071, 2024). "The results of this study have demonstrated the efficacy of EC359 in inhibiting the LIFR pathway and have established a critical function of LIFR signaling in mediating the effects of obesity on TNBC progression." (PMID 39518071, 2024). "The RNA-Seq analysis of xenograft models also confirmed critical pathways modulated by obesity via LIF/LIFR signaling, further elucidating the molecular mechanisms by which obesity influences TNBC progression." (PMID 39518071, 2024). "RNA-Seq analysis identified critical pathways modulated by LIF/LIFR signaling in diet-induced obesity mouse models." (PMID 39518071, 2024). "The ability of EC359 to attenuate LIFR signaling in the presence of ADP-CM, as well as in co-culture systems with adipocytes, indicates its broad applicability of targeting LIFR in disrupting obesity-enhanced signaling pathways in TNBC." (PMID 39518071, 2024). "This study investigated the potential impact of obesity on the advancement of TNBC by amplifying leukemia inhibitory factor receptor (LIFR) signaling." (PMID 39518071, 2024). "Further, this study is the first to establish a direct link between obesity, LIFR signaling, and TNBC progression." (PMID 39518071, 2024). "Mechanistic studies suggest that LIF/LIFR signaling plays an important role in obesity-driven EEC progression and the LIFR inhibitor, EC359, has the potential to suppress the tumor progression driven by increased adiposity found in obese patients." (PMID 36358818, 2022). "Treatment with the LIFR inhibitor EC359 abolished obesity-mediated increases in LIFR signaling in vitro and EEC progression in vivo." (PMID 36358818, 2022). "In this study, we examined the utility of EC359 in blocking obesity-mediated signaling that occurs via the LIF/LIFR axis." (PMID 36358818, 2022). "These emerging studies suggest the critical role of LIF/LIFR signaling in obesity-induced EC progression." (PMID 34400617, 2021). "We tested the effects of LIFR inhibition using EC359 on TNBC cells in obesity conditions." (PMID 39518071, 2024). "Importantly, the inhibition of LIFR with EC359 effectively blocks these oncogenic processes, suggesting that LIFR represents a potential therapeutic target for obesity-driven TNBC." (PMID 39518071, 2024). "This study explores the hypothesis that obesity upregulates leukemia inhibitory factor receptor (LIFR) oncogenic signaling in TNBC and assesses the efficacy of LIFR inhibition with EC359 in blocking TNBC progression." (PMID 39518071, 2024). "The role of LIF/LIFR signaling in obesity-mediated EEC progression remains unclear and is the focus of this study." (PMID 36358818, 2022). "We examined whether the recently developed LIFR inhibitor, EC359, has the ability to block obesity-induced LIF/LIFR-mediated proliferation and signaling in EEC." (PMID 36358818, 2022). "However, the role of LIF/LIFR signaling in the progression of obesity-driven TNBC remains elusive." (PMID 39518071, 2024). "Collectively, our data support the premise that LIF/LIFR signaling plays an important role in obesity-driven EEC progression and the LIFR inhibitor EC359 has the potential to suppress adipocyte-driven tumor progression." (PMID 36358818, 2022).
Obesity (continued). "In summary, these results demonstrate that obesity conditions enhance LIFR downstream signaling and increase invasion in TNBC cells, as evidenced by increased STAT3 reporter activity, increased LIFR target gene expression, elevated levels of signaling proteins, and enhanced invasion." (PMID 39518071, 2024). "In this study, we tested the hypothesis that obesity enhances LIFR signaling in TNBC, contributing to cancer progression, and tested the therapeutic potential of LIFR inhibition using the small-molecule inhibitor EC359." (PMID 39518071, 2024). "Obesity signaling enhances E2 biosynthesis and E2 function as a potent inducer of leukemia inhibitory factor (LIF), which mediate its signaling using a receptor complex comprising LIFR and glycoprotein 130 (gp130)." (PMID 36358818, 2022).
liver cancer (6 papers, 2015 to 2024). An epithelial or non-epithelial malignant neoplasm that arises from the liver. "The LIFR gene is significantly underexpressed in liver cancer and has a significant tumor suppressor effect in liver cancer." (PMID 36176304, 2022). "Consistently, LIFR overexpression in the PLC/PRF/5 human liver cancer cell line led to downregulation of IKKα/β phosphorylation and upregulation of IκBα protein levels, and these effects were abolished by knockdown of SHP1." (PMID 34921145, 2021). "The liver cancer cell line data from the CTRP revealed a significant correlation between LIFR expression and the sensitivity to erastin, which targets the cystine transporter SLC7A11 to induce ferroptosis." (PMID 34921145, 2021). "Leukemia inhibitory factor receptor (LIFR) is frequently downregulated in liver cancer." (PMID 34921145, 2021). "Notably, knockout of Lifr drastically increased p65 phosphorylation in PHM cells, which could be reversed by re-expression of LIFR; the same effect was observed in LIFR-knockdown human liver cancer cell lines, Mahlavu and PLC/PRF/5." (PMID 34921145, 2021). "Indeed, overexpression of LIFR sensitized PLC/PRF/5 cells to erastin or sorafenib, which could be reversed by co-treatment with liproxstatin-1, DFO, or purified LCN2 protein, indicating that LIFR sensitizes liver cancer cells to ferroptosis inducers through iron and LCN2." (PMID 34921145, 2021).
colon cancer (5 papers, 2013 to 2025). "The three CpG sites specific to colon cancer were found to be uniquely associated with the leukemia inhibitory factor receptor (LIFR) gene." (PMID 39634131, 2025). "We analyzed the colon cancer cell lines along with a normal colon cell line (CCD-18co) for LIFR promoter methylation and mRNA expression." (PMID 28751909, 2017). "The colon cancer-specific methylation at LIFR and MLH1 promoters was verified by combined bisulfite restriction analysis (COBRA), a method used to determine DNA methylation levels at a specific genomic locus using restriction endonucleases." (PMID 28751909, 2017). "CpGs at the LIFR gene promoter, which are known to be hypermethylated in colon cancers, indeed were heavily methylated in the tested colon cancer cells." (PMID 28751909, 2017). "In the case of LIFR cg03723506, the difference in methylation level between the colon cancer and normal samples was remarkable (p < 2.2 × 10-16; Wilcoxon rank sum test)." (PMID 28751909, 2017). "A meta-analysis with public cancer methylome data verified the colon cancer specificity of LIFR promoter methylation." (PMID 28751909, 2017). "The COBRA result showed that the LIFR cDMC was unmethylated in the CCD-18co control cells whereas it was heavily methylated in most colon cancer cell lines." (PMID 28751909, 2017). "The 200 CpGs also included three known colon cancer-specific biomarkers (LIFR, OSMR, QKI)." (PMID 38336771, 2024). "The LIFR CpGs were previously reported to be specifically methylated in colon cancer samples." (PMID 28751909, 2017). "Furthermore, the promoter methylation correlated with downregulation of the LIFR gene expression, which leads to a speculation of the importance of LIFR suppression in the development of colon cancer development." (PMID 28751909, 2017). "Other non-colon cancer cell lines such as SNU449 liver cells which were not methylated at the LIFR cg03723506 cDMC also expressed the LIFR and LIFR-AS genes." (PMID 28751909, 2017). "RT-PCR result showed that both the LIFR and LIFR-AS transcripts were detected in the normal CCD-18co cells only but not in the other colon cancer cell lines." (PMID 28751909, 2017).
Stroke (5 papers, 2018 to 2025). Sudden impairment of blood flow to a part of the brain due to occlusion or rupture of an artery to the brain. "The dual properties of LIFR signaling make it a promising therapeutic target for stroke and other neurological injuries." (PMID 39734575, 2024). "Our findings suggest that LIF/LIFR interactions mediate beneficial effects of CD8+ TRLs early after stroke." (PMID 35912857, 2022). "Flow cytometric analysis confirmed that CD8+ TRLs exhibited increased expression of LIFR protein after entering the stroke brain." (PMID 35912857, 2022). "The LIFR mediates the beneficial effects of CD8+ TRLs after stroke." (PMID 35912857, 2022). "Since levels of LIFR in the brains of aged female rats were lower than those of aged male rats after stroke, the partial recovery observed in aged female rats after LIF treatment may be attributed to stronger anti-inflammatory activity." (PMID 33376583, 2020). "This study on aged animals also includes the use of flow cytometry to determine whether ischemic conditions alter the expression of LIFR on subpopulations of immune cells after stroke." (PMID 30322390, 2018). "LIFR is degraded after prolonged stimulation with LIF in many cell types, which indicates that the splenocytes were responsive to peripherally administered LIF after stroke." (PMID 30322390, 2018). "Therefore, examining expression of LIFR among leukocyte populations might provide further insight into how LIF promotes anti-inflammatory signaling in splenocytes and peripheral blood leukocyte after stroke." (PMID 30322390, 2018). "Although this laboratory has previously shown that the decrease in spleen size is observed as early as 24 h after stroke, this laboratory did not observe any LIF-mediated alteration in LIFR expression or spleen size prior to the 72-h time point." (PMID 30322390, 2018).
Alzheimer disease (4 papers, 2014 to 2024). A progressive, neurodegenerative disease characterized by loss of function and death of nerve cells in several areas of the brain leading to loss of cognitive function such as memory and language. "In the brains of Alzheimer’s disease (AD) and Parkinson’s disease (PD) patients, LIFR expression is higher than in the control brains." (PMID 39683685, 2024). "In neurodegenerative diseases such as Alzheimer's disease and Parkinson's disease, the role of LIFR in neuron survival becomes particularly crucial." (PMID 38819224, 2024).
endometrial cancer (4 papers, 2021 to 2023). Primary or metastatic malignant neoplasm involving the endometrium (mucous membrane that lines the endometrial cavity). "Finally, we detected an effect of LIFR on Uterine Corpus Endometrial Carcinoma (UCEC) and evaluated the expression level of LIFR in clinical UCEC samples." (PMID 36925915, 2023).
glioblastoma (4 papers, 2015 to 2023). The most malignant astrocytic tumor (WHO grade IV). "They demonstrated that macrophages induce the MES-like glioblastoma cell state via the macrophage-derived oncostatin M (OSN) and its receptors (OSNR and LIFR) expressed by glioblastoma cells." (PMID 34571910, 2021). "Macrophage-derived OSM promoted glioblastoma cells' mesenchymal transition by targeting LIFR." (PMID 36494582, 2023).